LINC00967 (long independently transcribed non-coding RNA 967)
Gene: Long non-coding RNA gene on chromosome 8 (66,177,238 to 66,200,904, forward strand). Ensembl gene ENSG00000253138.
Diseases named in the same sentence as LINC00967 in open-access papers:
LINC00967 is named in the same sentence as 1 disease in open-access papers, as found by Europe PMC text mining. Sharing a sentence is not in itself a finding about the gene and the disease.
LINC00967 shares sentences with these, for which no sentence is quoted: bladder cancer (1 paper).